USP17L6P (ubiquitin specific peptidase 17 like family member 6, pseudogene)
Description:
Deubiquitinating enzyme that removes conjugated ubiquitin from specific proteins to regulate different cellular processes that may include cell proliferation, progression through the cell cycle, cell migration, and the cellular response to viral infection. Seems to be non-functional in the regulation of apoptosis.
Synonyms: DUB4; vDUB4; USP17L6
Gene: Unprocessed pseudogene on chromosome 4 (9,367,874 to 9,369,070, forward strand). Ensembl gene ENSG00000205946.
Subcellular location: Nucleus; Cytoplasm
Diseases named in the same sentence as USP17L6P in open-access papers:
USP17L6P is named in the same sentence as 1 disease in open-access papers, as found by Europe PMC text mining. Sharing a sentence is not in itself a finding about the gene and the disease.
USP17L6P shares sentences with these, for which no sentence is quoted: cancer (1 paper).